TNF (tumor necrosis factor)
Diseases named in the same sentence as TNF in open-access papers (continued):
Sharing a sentence is not in itself a finding about the gene and the disease.
depression (continued). "In addition, venlafaxine has been reported to play an anti-inflammatory role through downregulation of serum TNF-α, IL-1β, IL-6, and CRP in major depressive disorder and animal researches." (PMID 35664492, 2022). "On average, individuals with clinical depression showed a non-significant trend for higher Tumor necrosis factor alpha (TNF-α) levels compared to controls." (PMID 35360574, 2022). "Group differences regarding TNF-α but not IL-6 were observed, and partial correlation analysis indicated an association between TNF-α and clinician-rated depression scores over the complete sample when controlling for age, weight, and height." (PMID 35444568, 2022). "Specifically, anti-TNF-α therapy was found not to be effective in all treatment-resistant depression patients, but it did improve depressive symptoms in those with higher baselines of inflammatory markers." (PMID 35782423, 2022). "In addition, peripheral increased cytokines such as tumor necrosis factor (TNF)-α and interleukin (IL)-6 have been reported in individuals with the comorbidity of depression and pain." (PMID 35370832, 2022). "Microglia are significantly stimulated in the CNS and peripheral blood of animal models of depression such as CSDS and CUMS, and pro-inflammatory cytokines including TNF-α, IL-1 β, and IL-6 are also significantly elevated in the brain, according to a preclinical study." (PMID 35634375, 2022). "These genes are involved in the complex pathological mechanism of depression, including the neurotransmitter system (e.g., HTR2A and SLC6A4), neurotrophin (e.g., BDNF), hypothalamic-pituitary-adrenal (HPA) axis (e.g., CRH), and inflammation (e.g., IL6, TNF)." (PMID 36072347, 2022). "In addition, proinflammatory cytokines such as IL-1, IL-6, TNF-α, and interferon (IFN)-γ enter the brain through multiple pathways to mediate depression-related psychiatric symptoms." (PMID 35813953, 2022). "In fact, these studies saw significant correlations between depression and other inflammatory markers such as IL-6 and TNF-α, but not CRP." (PMID 35618889, 2022). "As for NSCLC patients, only one previous study unravels that TNF‐α is higher in stage IV NSCLC patients with major depressive disorder than those without major depressive disorder." (PMID 34697903, 2022). "In a study of refractory depression, infliximab, a TNF-α inhibitor, did not have generalizable benefit in the treatment of refractory depression, but did result in clinical benefits in patients with elevated CRP at baseline." (PMID 36704001, 2022). "The investigation of 38 depression studies found that monocyte-derived, and other inflammatory cytokines (IL-1, IL-4, IL-6, and TNF) were significantly overexpressed in individuals with depression, while T cell derived cytokines (IL-10, and INF-γ) were uncorrelated with depression." (PMID 36206293, 2022). "Similarly to manic episodes, serum levels of many inflammatory markers (CRP, TNF‐α, IL‐6, IL‐1β, sTNFR1, and CXCL10) are elevated during depressive episodes, and this alteration correlates with increased depression severity." (PMID 34590391, 2022). "A recent study investigated associations between levels of six cytokines (IL-1β, eotaxin, IL-15, IL-6, TNF-α, and leptin) and chronic multisite pain (CMP) in a sample of people living with HIV, but also incorporated PHQ-9 scores as a measure of depression in their regression models." (PMID 35618889, 2022). "In relevant trials, high levels of interleukin (IL)-6 and tumor necrosis factor-alpha were found in HF patients with CD and depression, but not in HF patients free from these symptoms." (PMID 35887772, 2022). "Moreover, the cytokines that appeared increased in plasma after ISO, TNFα, IL6, and IL1β, are also the ones shared between depression and heart failure." (PMID 35936761, 2022).
depression (continued). "To investigate the differences in the expression of inflammatory factors in the serum of normal person, patients with depression, and patients with DCMI, we performed ELISA to detect the levels of NPY, T, IL-1β, IL-6, TNF-α, IL-10, and IL-4 in the peripheral blood plasma." (PMID 35432561, 2022). "Moreover, mental stress has been shown to increase the levels of several cytokines, such as tumor necrosis factor-alpha (TNF-α) and interleukin-1 (IL-1) to trigger neuroinflammation and induce depression or anxiety." (PMID 35783147, 2022). "Besides, the baseline TNF-α level was significantly higher and IFN-γ, IL-4, and IL-2 were lower in patients with depression compared with the HC group." (PMID 35722555, 2022). "Overactivation of inflammatory responses and increased levels of inflammatory mediators like interleukin (IL)−1β, IL‐6, tumor necrosis factor alpha (TNF‐α), the acute phase reactant (CRP), and high mobility group box 1 (HMGB1) were seen in both patients and rodents with depressive disorder." (PMID 35089644, 2022). "Neither the logIC IL-6, logEC IL-10, and logIC TNF-α values at baseline, follow-up, nor their overall courses significantly correlated with depression severity scores or course measured by the BDI-II or the HAMD (data not shown)." (PMID 33447872, 2021). "However, our use of clinical groups also had a number of inherent weaknesses: For example, we did not enrich the arthritis group for depression at baseline, which may underlie why we observed only a modest reduction in HADSd (~1.5 points or 24%) following anti-TNF." (PMID 32457424, 2021). "In accordance with the findings, the IL-1β, TNF-α, and IL-6 levels in the group with depression exceeded those without depression, and the high level of IL-6 contributed to memory impairment in the depressive group." (PMID 34299040, 2021). "Moreover, has_circ_0014220, has_circ_0014221, and their host gene S100A9 enriched in the IL-17 signaling pathway, augmented levels of the inflammatory cytokines IL-6, TNF-α, and IFN-γ in depression patients as well as tumor-bearing mice with CUMS." (PMID 34650925, 2021). "Also, in the astroglial degeneration model of depression, L-AAA-injected mice showed elevated TNF-α." (PMID 33628324, 2021). "Patients with remitted MDD, who had not suffered from depression for at least 12 months, had lower GR sensitivity (measured by logIC TNF-α) than patients currently undergoing an MDE." (PMID 33447872, 2021). "In our study, neither multimodal depression inpatient treatment nor AE by itself resulted in any effects on TNF-alpha." (PMID 33805073, 2021). "Thus, proinflammatory cytokines and molecules such as TNF-α, IL-6, interleukin 1 (IL-1), soluble interleukin 2-receptor (sIL-2R), and C-reactive protein (CRP) measured in serum are increased in patients with depression as compared to healthy subjects." (PMID 34764926, 2021). "Additionally, given interest in other potential markers of inflammation in relation to depression treatment response, we also explored relationships between several other inflammatory markers including CRP, IL-6, IL-10, TNF-α, and ketamine treatment outcome." (PMID 33723220, 2021). "For example, our group recently showed elevated immune markers (Interleukin (IL)-6, IL-10, Tumor Necrosis Factor (TNF)-α and Vascular Endothelial Growth Factor) in pregnant women with a diagnosis of major depressive disorder, compared with healthy pregnant controls." (PMID 34704078, 2021). "Due to the multifaceted pathogenesis of depression, this study aimed to clarify whether the KBD formula ameliorated the effect of UCMS-induced changes in expression levels of the depression-related genes BDNF, CREB, GR, SGK1, FKBP5, IL-1β, IL-6, and TNF-α." (PMID 34358084, 2021). "In absence of neuroinflammation, the role of TNF levels in serum in inducing depression-like behavior was demonstrated in a murine model of experimental chronic Chagas disease." (PMID 34610039, 2021).
depression (continued). "In the cotreatment model, giving memantine concomitantly during the paclitaxel treatment led to a potentially better suppression of peripheral TNF-α and IL-1β and tissue TNF-α expression, thus leading to a better reversal of mood symptoms and prevention of depression-like behavior." (PMID 34439331, 2021). "Moreover, IL-6 together with TNF-α is considered a mediator of systemic COPD effects (cachexia, skeletal muscle dysfunction, cardiovascular diseases, depression, hypodynamia, and osteoporosis), leading to an unfavorable outcome." (PMID 32089881, 2020). "Furthermore, other studies illustrated that depression and acute graft-versus-host-disease (GVHD) share common pro-inflammatory reactions: increment of inflammatory cytokines (i.e. tumor necrosis factor-alpha) and shifting toward T helper 1 response system." (PMID 32943660, 2020). "Based on these reports, it was suggested that peripheral blood IL-1β, IL-6, TNF, and CRP could constitute reliable biomarkers of inflammation in patients with depression." (PMID 32380663, 2020). "Positive correlations of the pro-inflammatory cytokine TNF-α with psychosocial and cognitive fatigue as well as with the severity of the depression were found in depressed, but not in non-depressed participants." (PMID 32528052, 2020). "High IFNγ and IL10 also predicted better HADS “depression” outcome, albeit with lower R2 than TNFα in the confounder controlled model (not shown)." (PMID 33240126, 2020). "Moreover, increased expression of various innate immune genes, including IL-1β, IL-6, TNF, TLR3, and TLR4, have been found in post-mortem brain samples from suicide victims that had depression." (PMID 32380663, 2020). "Numerous studies conducted on patients meeting the criteria of the Diagnostic and Statistical Manual of Mental Disorders (DSM) for major depression have found significant increases in plasma or serum levels of CCL2, IFNγ, IL-1α, IL-1β, IL-2, IL-6, IL-8, IL-12 and TNF-α, together with CRP." (PMID 32545890, 2020). "In in vitro and in vivo models of depression, BDNF was shown to improve depressive-like behavior by upregulating anti-inflammatory cytokine IL-10, IL-4, and TGF-β1 and downregulating the pro-inflammatory cytokine IL-1β, IL-17, and TNF-α." (PMID 32256638, 2020). "Fifth, we took the most important confounders available, such as depression, DST non-suppression status, CTQ total score and plasma levels of TNF-alpha, into consideration, in association analyses between methylation and hypersexuality." (PMID 31542994, 2020). "In clinical patients, the release of pro-inflammatory cytokines, especially interleukin-1 cytokines (IL-1) and tumor necrosis factor (TNF-), is higher in depressed patients compared with normal patients, indicating that inflammation plays an vital role in the pathophysiology of depression." (PMID 32460706, 2020). "Interestingly, this decrease is accompanied by decreased IL-10 and C-C chemokine ligand 5 (CCL5/RANTES) but increased TNF-α in the PFC in a co-model of pain and depression induced by spinal nerve ligation and olfactory bulbectomy model." (PMID 32849076, 2020). "Elevated levels of proinflammatory cytokines, especially interleukin-1β (IL-1β), interleukin-6 (IL-6), and tumor necrosis factor alpha (TNF-α), can interact with the neuroendocrine function and influence neuronal function, which has been reported in depression." (PMID 32596383, 2020). "Furthermore, the levels of IL-1β, IL-6, TNF-α, and TGF-β are positively correlated with the symptoms of depression." (PMID 33613190, 2020). "In particular, pro-inflammatory cytokines like interleukin-2 (IL-2), IL-6, soluble IL-6 receptor, tumor necrosis factor-α (TNF-α) and interferon-γ (IFN-γ) are increased while anti-inflammatory cytokines like IL-4 and IL-10 are decreased during depressive disorders." (PMID 33066277, 2020).
depression (continued). "Additionally, increased expression of a variety of innate immune genes and proteins, including IL-1β, IL-6, TNF, Toll-like receptor 3 (TLR3) and TLR4, has been found in post-mortem brain samples from individuals with depression that died by suicide." (PMID 31647818, 2019). "The correlation with the reduction of depression symptomatology we observed for TNF-α, IL-6, and IL-10 levels is not fully consistent with the reported alterations of these cytokines after antidepressant treatment according to most recent meta-analyses." (PMID 31375659, 2019). "We therefore examined the effects of Aβ1-42 oligomers i.c.v. injection on the mRNA levels of pro-inflammatory cytokines (IL-1β and TNF-α) and anti-inflammatory cytokines (IL-4 and TGF-β1) in the hippocampus, a brain area of primary relevance in the pathogenesis of depression." (PMID 31293421, 2019). "According to the current literature, it seems that peripheral levels of interleukin (IL)-6, IL-10, IL-12, IL-13, and tumor necrosis factor (TNF)-α are elevated and that interferon (IFN)-γ levels are lower in patients with depression compared to healthy controls." (PMID 30792669, 2019). "It has been shown that an increased level of TNF-α and INF-γ in the blood plays a role in depression- and anxiety-like behaviors which may explain the significant results that we observed in the open-field task with HI rats comparing to sham." (PMID 31660990, 2019). "Therefore, the increased anxiety-related and depression-related behaviors displayed by defeated S1PR3 knock-down rats was due, at least in part, to increased TNFα." (PMID 31316053, 2019). "In the present study, we did not explore the relationship between 5-HT levels and TNF-α expression because we only attempted to identify the biochemical alterations of the comorbidity of pain and depression." (PMID 31616368, 2019). "Relative to the depression group, the miR-301b mimic and miR-301b mimic + PLX3397 groups showed obviously decreased expressions of NPTX2, and the miR-301b mimic group displayed increased expressions of p-NF-κB, TNF-α, IL-Iβ, and COX-2 (p < 0.05)." (PMID 30962417, 2019). "Recent evidence suggests that stress hormones may actually facilitate inflammation followed by depression, through induction of various cytokines including IL-1, IL-6, IL-8, IL-18 and TNF (tumor necrosis factor)." (PMID 31150403, 2019). "We had found that there were significant interactions between the withdrawn/depression item reported on the CBCL-C scale and TNF-α (p = 0.027) and between the thought problems item on the CBCL-C scale and TNF-α (p = 0.028) in subjects who had received DM-MPH treatment (data not shown)." (PMID 31333511, 2019). "In addition, the pretreatment Beck Depression Inventory, P2 LDAEP, and N1/P2 sLORETA-LDAEP were greater in the high-TNF-α groups than in the low-TNF-α groups (p < 0.05)." (PMID 31561419, 2019). "Significant interactions were found between the withdrawn/depression item reported on the CBCL-C scale and tumor necrosis factor α (ခTNF-α) (p = 0.027), as well as between thought problems item on the CBCL-C and TNF-α (p = 0.028) in subjects who had received DM+MPH treatment." (PMID 31333511, 2019). "Patients with depressive disorders were reported to have a higher serum concentration of inflammatory markers, including interleukin (IL)-6, tumor necrosis factor (TNF)-α and IL-1β, compared with those without depressive disorders." (PMID 31765424, 2019). "In this meta-analysis, we found that elderly with depression had significantly higher peripheral levels of IL-1β (p = 0.026), IL-6 (p < 0.001) but not TNF-α (p = 0.351) and CRP (p = 0.05)." (PMID 30104698, 2018). "Furthermore, pro-inflammatory cytokines, including interleukin-6 and tumor necrosis factor alpha (TNF-α), were found to be elevated in depression." (PMID 29723340, 2018).
depression (continued). "And that the pro-inflammatory cytokines IL-1, IL-6, and tumor necrosis factor alpha (TNF-α), as well as C-reactive protein (CRP), may contribute to the initiation and progression of psychiatric diseases, such as depression." (PMID 30319458, 2018). "Findings indicate that depression was not related to levels of circulating cytokines among patients in treatment, but that traumatized patients had higher levels of IL-1RA and TNF-α than patients without trauma experience." (PMID 29631540, 2018). "The domination of M1 phenotype exaggerates neuroinflammation through releasing pro-inflammatory cytokines, such as IL-1β and TNF-α, but suppresses anti-inflammatory cytokines like IL-10 and TGF-β, which may contribute to the etiology of depression." (PMID 30248907, 2018). "In addition, IL-10 decreased in mPFC and BA, while IL-1β and TNF-α protein expression increased in mPFC, BA, and VH on POD 45, which indicated a CNS shift to pro-inflammatory profile at the time when anxiety- and depression-related behaviors were observed." (PMID 30208926, 2018). "Further, some cytokines such as interleukin- (IL-) 1β, IL-6, and tumor necrosis factor-α (TNF-α) were believed to be contributors of the onset and progression of depression because these cytokines affected the neuron function and neuroactive molecule production which were associated with depression." (PMID 29765402, 2018). "TNF-α, IFN-γ, IL-5, IL-12, and IL-13 were further related to the severity of depressive symptoms, as well as the somatic-affective and the cognitive dimensions of depression." (PMID 30524320, 2018). "Levels of BDNF, hsCRP, IL-6 and TNF-α are able to discriminate either euthymia or depression by being no different in that mood phase in comparison with levels in controls but altered in other mood phases." (PMID 30113291, 2018). "In this meta-analysis, peripheral levels of TNF-α were not significantly increased in elderly with depression as well as Alzheimer’s disease as compared to controls before and after Bonferroni adjustment." (PMID 30104698, 2018). "In AD with depression group, a moderate inverse correlation was seen between serum IL 6 levels and MMSE score (r = - 0.47, p = 0.0048), while a strong inverse correlation existed between serum TNF α levels and MMSE scores (r = - 0.65, p = 0.0001)." (PMID 28580183, 2017). "Depression in women was associated with a larger waist circumference and higher levels of adiposity/T2DM related markers specifically HOMA IR, leptin and TNF-α compared with women without depression." (PMID 29190710, 2017). "Rats with depression-like phenotype displayed higher serum levels of IL-1β, IL-6 and TNF-α than rats without depression-like phenotype (P < 0.05)." (PMID 28600519, 2017). "Another interesting and significant correlation is seen between the levels of vitamin D and IL 6 or TNF α in the AD with depression group, but not in controls or AD without depression." (PMID 28580183, 2017). "Besides TNF-α, the brain-derived neurotrophic factor (BDNF) has also been considered as a depression biomarker and its plasmatic levels were evaluated." (PMID 28056040, 2017). "When these parameters were compared between two sub groups of AD subjects, it was observed that serum IL 6 and TNF α levels were significantly higher (p<0.001 and p<0.0006 respectively) in depressive AD patients than their counterparts without depression." (PMID 28580183, 2017). "In depressed females, but not depressed males, levels of IL-1β and TNF-α positively correlated with the severity of overall depression measured by the MADRS, and also with three individual items of the MADRS: lassitude, pessimism, and suicidal thoughts." (PMID 28670290, 2017). "In this study, we observed increased levels of proinflammatory cytokines of IL-6, IL-1β, TNF-α as well as anti-inflammatory cytokines of IL-4 and IL-10 in the rats with depression-like phenotype, but not rats without depression-like phenotype." (PMID 28600519, 2017).